ECI1 (enoyl-CoA delta isomerase 1)
Description:
Auxiliary enzyme in the beta-oxidation of mono- and polyunsaturated fatty acids. Together with the 2,4-dienoyl-CoA reductase (DECR) and the Delta(3,5)- Delta(2,4)-dienoyl-CoA isomerase (ECH1), they allow the reentrance of the enoyl-CoA into the beta-oxidation cycle. Able to isomerize both 3-cis (3Z) and 3-trans (3E) double bonds into the 2-trans (2E) form in a range of fatty enoyl-CoA species, with a preference for (3Z)-enoyl-CoAs over (3E)-enoyl-CoAs. The catalytic efficiency of this enzyme is not affected by the fatty acyl chain length, and based on its established catalytic mechanism, it is predicted to act also on other fatty acids besides those tested experimentally (By similarity).
Synonyms: DCI
Tractability: Small molecule: a structure with a bound ligand is known; it has a high-quality binding pocket. PROTAC: ubiquitination databases record sites on it; its protein half-life has been measured.
Target class: Isomerase; Enzyme
Gene: Protein-coding gene on chromosome 16 (2,239,402 to 2,252,300, reverse strand). Ensembl gene ENSG00000167969.
Subcellular location: Mitochondrion matrix
Subcellular location (Human Protein Atlas): Mitochondria
Pathways (Reactome):
Metabolism: mitochondrial fatty acid beta-oxidation of unsaturated fatty acids
Metabolism of proteins: Mitochondrial protein degradation
Gene Ontology:
Molecular function: delta(3)-delta(2)-enoyl-CoA isomerase activity; intramolecular oxidoreductase activity, transposing C=C bonds; catalytic activity
Biological process: fatty acid beta-oxidation
Cellular component: mitochondrion; mitochondrial matrix
Genetic constraint (gnomAD): Loss-of-function variants: 33 observed, 29.71 expected, observed/expected ratio (o/e) 1.11, 90% interval 0.84 to 1.49. The synonymous counts are far from expectation, so gnomAD's model fits this gene poorly and the ratio says little. Missense variants: 448 observed, 375.58 expected, observed/expected ratio (o/e) 1.19, 90% interval 1.1 to 1.29. Synonymous variants: 211 observed, 166.75 expected, observed/expected ratio (o/e) 1.27, 90% interval 1.13 to 1.42.
Homologues: Orthologues: chimpanzee ECI1 (98% identical), macaque ECI1 (89% identical), dog ECI1 (78% identical), pig ECI1 (76% identical), guinea pig ECI1 (73% identical), rat Eci1 (73% identical), mouse Eci1 (71% identical), rabbit ECI1 (67% identical), tropical clawed frog eci1 (59% identical), zebrafish eci1 (55% identical), Drosophila melanogaster CG4598 (36% identical), Drosophila melanogaster CG4594 (35% identical), and 1 more. Paralogues in human: AUH (24% identical), ECHDC2 (21% identical), ECH1 (20% identical), CDYL (19% identical), ECHDC3 (19% identical), ECHDC1 (19% identical), CDY1B (18% identical), HIBCH (18% identical), CDY2A (18% identical), CDY2B (18% identical), CDYL2 (18% identical), ECHS1 (18% identical), and 1 more.
Diseases named in the same sentence as ECI1 in open-access papers:
ECI1 is named in the same sentence as 20 diseases in open-access papers, as found by Europe PMC text mining. Sharing a sentence is not in itself a finding about the gene and the disease. The quoted sentences say what the papers report.
age-related macular degeneration (1 paper, 2024). Age-related loss of vision in the central portion of the retina (macula), secondary to retinal degeneration. "Five of these proteins (protein-coding genes ECI1, LCT, and NPTXR for glaucoma, WARS1 for age-related macular degeneration (AMD), and SIGLEC14 for diabetic retinopathy (DR)) are newly reported." (PMID 39408566, 2024).
cardiac hypertrophy (1 paper, 2020). "Fatty acid oxidation (Acadm, Etfdh, Acadl, Acadvl, Eci1, Hadh, Phyh, Acaa2, Hadha, Hadhb, Cd36), glucose metabolism (Dld, Pdha1, Pgam1, Pgam2, Acss1, Ldhb, Fh1, Slc2a4, Aldh6a1), TCA cycle (Aco2, Dld, Fh1, Ogdh, Sucla2, Sdha, Idh3b, Idh2) were up-regulated by hispidulin in cardiac hypertrophy." (PMID 33324687, 2020).
Cognitive impairment (1 paper, 2013). Abnormal cognition is characterized by deficits in thinking, reasoning, or remembering. "ECI1, involved in beta-oxidation of unsaturated fatty acids, could be contributing to the patient's mild cognitive impairment; however, this seems unlikely given the absence of developmental regression or metabolic crises." (PMID 23936691, 2013).
glaucoma (1 paper, 2024). Increased pressure in the eyeball due to obstruction of the outflow of aqueous humor. "A total of 11 unique protein-coding genes posterior probability (PP) of H4 > 0.70 finally remained, including GSTM3 for senile cataract, WARS1, C3, IGFBP7, and PILRA for AMD, ECI1, LCT, and NPTXR for glaucoma, EFEMP1 for myopia, and SIRPG and SIGLEC14 for DR." (PMID 39408566, 2024).
heart failure (1 paper, 2026). Inability of the heart to pump blood at an adequate rate to meet tissue metabolic requirements. "Thus, FTO modulates Eci1 expression through m6A-dependent mechanisms, facilitates fatty acid metabolism and mitigates pressure overload-induced heart failure during exercise." (PMID 41594638, 2026).
neonatal respiratory distress syndrome (1 paper, 2013). "ECI1 and ABCA3 would only be expected to cause disease in an autosomal recessive fashion, likely explaining the lack of any history of neonatal respiratory distress syndrome and/or metabolic disease." (PMID 23936691, 2013).
prostate carcinoma (1 paper, 2022). A carcinoma that arises from epithelial cells of the prostate gland. "Studies showed that over-expression of ECI1 are related with the risk of distant metastasis and reduced survival in prostate cancer patients." (PMID 36304471, 2022).
tumor (6 papers, 2017 to 2025). "As a result, ACAT1, ADH4 and ECI1 were even more down-regulated in HBV-positive HCC tumor tissue, and ACAT1, ADH4 and ACSL3 were down-regulated in HepG2.2.15 to a higher degree." (PMID 37957550, 2023). "In general, proteins involved in fatty acid β-oxidation such as hydroxysteroid (17-beta) dehydrogenase 10 (HSD17B10), enoyl-CoA hydratase, short chain, 1, mitochondrial (ECHS1), enoyl-CoA delta isomerase 1 (ECI1) were down- regulated in tumour-bearing animals (p-value < 0.001)." (PMID 29258509, 2017).
ECI1 also shares sentences with these, for which no sentence is quoted: cancer (2 papers); breast carcinoma (1); diabetic retinopathy (1); dyslipidemia (1); hepatitis C virus infection (1); infection (1); kidney tumor (1); liver disease (1); metabolic disease (1); myopia (1); Obesity (1); ovarian carcinoma (1).